PLG (plasminogen)
Diseases named in the same sentence as PLG in open-access papers (continued):
Sharing a sentence is not in itself a finding about the gene and the disease.
infection (73 papers, 2007 to 2026). The state of being infected such as from the introduction of a foreign agent such as serum, vaccine, antigenic substance or organism. "Beside colonization, dissemination through the human host and establishment of an infection is often accompanied with the ability of pathogenic bacteria to recruit soluble activatable precursor molecules from the circulation like plasminogen." (PMID 38726006, 2024). "It is worth noting that, in addition to its key fibrinolytic function, plasminogen also plays a crucial role in the behavior of cells in immune and inflammatory processes, including reducing the risk of infection and providing antiviral protection." (PMID 38248359, 2023). "We found that the “subverted” plasminogen system plays an important role in development of invasive infection caused by C. albicans in mice." (PMID 33115324, 2020). "Mutation of the plasminogen bringing site of enolase reduced the bacterial virulence of S. pneumoniae in a murine intranasal infection model." (PMID 28018326, 2016). "Activation of the plasminogen system causes degradation of the extracellular matrix and facilitates spreading of bacteria and invasive infection." (PMID 26018417, 2015). "This suggests that plasminogen plays a minor role in replication of this virus, while plasminogen deficiency still protected from infection with this virus." (PMID 23555246, 2013). "To further confirm if the deleterious role of plasminogen is caused by fibrinolysis, we tested the outcome of infection of mice after treatment with Ancrod and/or 6-aminohexanoic acid (6-AHA)." (PMID 23555246, 2013). "Infection studies in plasminogen-deficient and fibrinogen-deficient mice support the essential role of plasminogen as a Pla substrate." (PMID 23898467, 2013). "In contrast, a noticeable increase in hBMECs detachment was observed at 120 min post-infection with plasminogen-treated GBS that was associated with a 50% decrease in hBMECs viability (P<0.0001)." (PMID 23658816, 2013). "We conclude that the pathomechanism of plasminogen activation is conserved in oral streptococci that cause infections in human." (PMID 21072208, 2010). "Binding of plasminogen by α-enolase and its subsequent activation has been demonstrated to promote invasion of pathogenic bacteria and therefore represents an important determinant of virulence in invasive infection." (PMID 24478765, 2014). "Thus, blocking plasminogen-mediated fibrinolysis protected mice against infections with various and highly pathogenic IAVs." (PMID 23555246, 2013). "Here, we investigated the interaction between NS1 and plasminogen, the precursor of the fibrinolytic enzyme plasmin, aiming to characterize its implications in clot turnover during infection." (PMID 42054092, 2026). "It should be noted that the levels of serum MCP-1 were significantly higher in EV-71-infected WT mice than in PLG-KO mice at 4 and 6 days post-infection." (PMID 40377310, 2025). "To evaluate the effect of TXA treatment on the course of GAS infection, we employed a previously established intranasal infection model, using AlbPLG1 mice, which express human plasminogen." (PMID 41322414, 2025). "Previous studies have linked the acquisition of plasminogen (Plg) by GAS Fg‐binding M proteins to tissue destruction and excessive stimulation of the human inflammatory response during infection." (PMID 40100134, 2025). "The serum level of IFN-γ was significantly lower in WT mice than in PLG-KO mice at 6 days post-infection." (PMID 40377310, 2025). "Similar to the observation in serum, the spinal cord MCP-1 expression was significantly higher in EV-71-infected WT mice than in PLG-KO mice at 4 days post-infection." (PMID 40377310, 2025).
infection (continued). "This study found that PLG-KO mice are more resistant to EV-A71-induced clinical symptoms and have higher survival rates at 10 days post-infection." (PMID 40377310, 2025). "The mortality of EV-A71-infected PLG-KO mice (20%) was much lower than EV-A71-infected WT mice, in which 60% died within 11 days post-infection." (PMID 40377310, 2025). "Serum IL-10 level was significantly higher in EV-71-infected WT mice than in PLG-KO mice at 2 days post-infection." (PMID 40377310, 2025). "Although PLG is not a primary viral receptor that directly interacts with viral proteins, several studies have shown that PLG is a cofactor that facilitates virus binding or infection." (PMID 40377310, 2025). "The viral load of PLG-KO mice in the spinal cord was lower than that of WT mice at 6 days post-infection." (PMID 40377310, 2025). "The viral loads in the spinal cord of PLG knockout mice were lower than those in WT mice 6 days post-infection." (PMID 40377310, 2025). "Combined with our findings, which indicated that anti-PLG antibodies reduced the binding of EV-A71 to the cell surface, we propose that PLG is involved in EV-A71 infection and plays a beneficial role in EV-A71 binding as an attachment factor." (PMID 40377310, 2025). "In the spinal cord section of mock and PLG-KO mice, minimal to no detectable staining was observed, suggesting a protective effect of PLG-KO against EV-A71 infection (middle left and center)." (PMID 40377310, 2025). "We found that the clinical scores of WT mice were higher than those of PLG-KO mice and significantly elevated 6–8 days post-infection." (PMID 40377310, 2025). "The recombinant proteins studied interacted with PLG, a key host molecule in the fibrinolytic system employed by microorganisms for invasion and establishment of infection." (PMID 39659425, 2024). "It has been known for decades that S. pyogenes streptokinase is highly specific to human plasminogen, hampering the application of animal infection models." (PMID 39003250, 2024). "Other important strategies for the colonization and infection of the host have been reported for staphylococci and include the expression of adhesins on the bacterial surface, as well as the acquisition of host plasminogen and complement regulatory proteins." (PMID 35215183, 2022). "Bacterial GAPDH can interact with human hemoglobin and plasminogen to compete for hemin-iron and promote infection in the host cells." (PMID 35414267, 2022). "We found that the 6hpi and 12hpi time points for infection with the New York strain shared two dysregulated pathways including the activated “keratinization”pathway, and the inhibited “plasminogen activating cascade”." (PMID 36204651, 2022). "In this study, we analyzed the interaction between TpiA and plasminogen to investigate its involvement in infection." (PMID 35298875, 2022). "Recruitment of plasminogen is an important infection strategy of the human pathogen Streptococcus pneumoniae to invade host tissues." (PMID 35298875, 2022). "We found that the “plasminogen activating cascade” signaling pathway was shared between the 6hpi time points of infection with the New York and Washington strains." (PMID 36204651, 2022). "Plasminogen has been shown to be activated by dengue virus in vitro and plasminogen cross-reactive antibodies have been detected during infection." (PMID 32130212, 2020). "Plasmin cleaved from plasminogen by plasminogen activators can degrade extracellular matrix, in turn breakdown epithelial barriers and finally lead to bacterial invasion and infection." (PMID 31540175, 2019). "Curiously, some moonlighting proteins of Candida albicans also have the ability to bind plasminogen, which is relevant to infection." (PMID 29867878, 2018). "S. pyogenes and Staphyloccocus aureus release streptokinase and staphylokinase, respectively, two enzymes that can activate plasminogen and help the bacteria to disseminate from the site of infection streptokinase." (PMID 29520265, 2018).
infection (continued). "Homozygous individuals have a reduced plasminogen activity about 10% with fewer thrombotic events, but enhanced survival during infection by Y. pestis but also by group A streptococci and S. aureus requiring plasminogen activation for pathogenicity." (PMID 29197958, 2017). "A number of microorganisms of medical importance, including Staphylococcus aureus, acquire plasminogen and exploit plasmin proteolytic activity to aid tissue penetration and invasion during infection." (PMID 25409527, 2014). "The increasing amount of publications on bacterial-plasminogen interaction reflects the high relevance of this topic in infection biology." (PMID 24319673, 2013). "Especially the pathogenic species like GAS, S. pneumoniae, S. canis, and S. suis, benefit from plasminogen recruitment in the infection process." (PMID 24319673, 2013). "Remarkably, intranasal mouse infection studies demonstrated that plasminogen recruitment to pneumococci significantly contribute to virulence in mice." (PMID 24319673, 2013). "Since severe inflammation contributes to the pathogenicity of IAV infections of humans, most likely the proinflammatory properties of plasminogen play a role in the pathogenesis of these infections." (PMID 23555246, 2013). "Here, the mortality of transgenic mice expressing human plasminogen was markedly increased after infection with GAS." (PMID 24319673, 2013). "In PLG-KO mice substantial protection was also observed against infection with 2009 pandemic virus A/Netherlands/602/09 (30, 000 PFU) and highly pathogenic H5N1 virus A/chicken/Ivory-Coast/1787/2006 (10 EID50 H5N1)." (PMID 23555246, 2013). "To reveal the functional roles of plasmin in infection and sepsis, we used WT, plg+/-, and plg-/- mice, which exhibit 100%, 50%, and 0% of the normal serum plasminogen level, respectively." (PMID 21931850, 2011). "The plasminogen activation system was studied with several species of Borrelia and with Treponema denticola and suggested to have an important role during infection." (PMID 21755014, 2011). "In the case of spirochetes, the plasminogen activation system was studied with several species of Borrelia with Treponema denticola and suggested to have an important role during infection." (PMID 20582320, 2010). "Although the histone–plasminogen interaction occurs in a vertebrate infection system, further research should determine if additional arthropod-derived factors are involved." (PMID 20558510, 2010). "Our data provide an array of novel leptospiral receptors for human plasminogen, which constitutes an important step for the understanding of the molecular pathogenesis and infection process of these bacteria." (PMID 20582320, 2010). "Here we report that plasminogen activation is also common in oral streptococci species involved in clinical infection and that it depends on the action of human plasminogen activators." (PMID 21072208, 2010). "Thus, we evaluated serum cytokine levels, such as IL-1β, IL-6, IL-10, MCP-1, and IFN-γ in EV-A71 infected PLG-KO and WT mice at 2, 4, and 6 days post-infection." (PMID 40377310, 2025). "FtsZ could bind various host ECM and plasminogen, promoting the adhesion and spread of M. bovis during infection." (PMID 41388316, 2025). "The WT mice showed more muscle damage and inflammation following EV-A71 infection than the mock and the PLG-KO mice, which may lead to differences in disease outcome." (PMID 40377310, 2025). "Notably, the virus titers in the spinal cord of WT mice were significantly higher than PLG KO mice 6 days post-infection." (PMID 40377310, 2025). "We observed that PLG-KO mice expressed fewer clinical symptoms than WT mice and that the viral loads in the PLG-KO mice in some organs were also lower than those in the WT mice at 3 and 6 days post-infection." (PMID 40377310, 2025). "Therefore, PLG-mediated fibrinolysis increases vascular permeability, allowing the recruitment of inflammatory cells to the site of infection." (PMID 40377310, 2025).
infection (continued). "The importance of this species-specific interaction was illustrated by the observation that injection of mice with human plasminogen was sufficient to enhance virulence of S. pyogenes, and that transgenic mice expressing human plasminogen quickly succumb to infection by this organism." (PMID 39003250, 2024). "Thus, the ability of recombinant proteins to interact with PLG represents a crucial step in invasion and establishment of infection." (PMID 39659425, 2024). "Similarly, GAS streptokinase (SK) is a virulence factor that activates host plasminogen to facilitate pathogen spreading and dissemination from the initial site of infection into the surrounding tissues." (PMID 37872209, 2023). "It is likely that it would disseminate in the human body to form a systemic infection, as it does in pigs [1, 23, 35–38,], and the exploitation of the plasminogen/plasmin system might also participate in its infection in humans." (PMID 34082810, 2021). "Among proteins without PPIs, ENO is a relevant glycolytic enzyme that also activates plasminogen, and it is involved in the processes of infection and migration of the parasite, reducing the host immune function as well as preventing the immune attack of the host to the parasites." (PMID 35055970, 2021). "We first investigated that whether C. albicans could activate the host plasminogen system to facilitate invasive infection." (PMID 33115324, 2020). "In the present study, we first characterized that C. albicans cell wall-localized Eno1 could capture and “subvert” host plasminogen for facilitating invasive infection." (PMID 33115324, 2020). "Additionally, the enolase, a Zn-binding protein of these pathogens, interacts with host plasminogen favoring the invasion and dissemination steps during host tissue infection." (PMID 25620964, 2014). "To ensure that the observed GBS cell surface plasmin activity was due to binding and activation of the plasminogen present in human plasma, we determined at 300 min post-infection the proteolytic activity of GBS cells previously incubated with εACA prior to hBMECs infection." (PMID 23658816, 2013). "If binding by a cell surface molecule on a pathogen can result in activation of plasminogen to plasmin, then the binding-activation event might help disseminate the infection." (PMID 22174817, 2011). "Differences in plasminogen activation by streptococci may crucially influence the pathogenesis of infection." (PMID 21072208, 2010). "The goal of the studies described here was to determine whether FT has the potential to use the host fibrinolytic system (specifically PLG) to enhance its ability to penetrate/disseminate following infection of a mammalian host." (PMID 20226053, 2010). "Several transcripts related to the process of fibrin dissolution, including those for urokinase plasminogen activator (uPA) and uPA receptor, as well as the plasminogen activator inhibitor type 1 of the plasminogen-cleaving serine proteases, increased during days 4 to 6 after infection." (PMID 17725815, 2007). "In addition, the binding of PLG to cell surface receptors may facilitate EV-A71 attachment and activate PLG to form plasmin, which participates in EV-A71-infection-induced cytokine storms." (PMID 40377310, 2025). "Furthermore, inhibition of plasminogen activation by PAI-1 strongly blocks infection in both hosts." (PMID 35618711, 2022). "The finding of higher lenA transcripts among upshifted cultures of Portlandvere alludes to the possible involvement at early onset of infection possibly in host recognition to facilitate adhesion, bind plasminogen, overcome host derived ROS, and/or other unknown functions." (PMID 28536558, 2017).
infection (continued). "Bacteria exploit the proteolytic activity of the plasminogen system to overcome physical barriers formed by the host's extracellular matrix and the coagulation system when invading host tissue; a prerequisite for successful infection and bacterial dissemination." (PMID 21072208, 2010). "LppA interacts with multiple ECM components, host plasminogen, and ANXA2, promoting M. bovis colonization and spread during infection." (PMID 37978536, 2023). "GAS interacts with various host serum factors, including fibrinogen, fibronectin, immunoglobulins, plasminogen, factor H, and C4BP, and this binding activity contributes to many steps in colonization and infection processes." (PMID 32694142, 2020). "Our KEGG pathway enrichment analysis indicates that the up-regulated DEGs including C3, PLG, CFD, CR1, and C1QB are still enriched in complement and coagulation cascades, up to 24 h after infection." (PMID 31316336, 2019). "Collectively, we propose a model in which plasminogen-mediated fibrinolysis increases FDP production and vascular permeability allowing increase recruitment of inflammatory cells at the site of infection." (PMID 23555246, 2013). "Collectively, these results suggest that plasminogen plays an important role in promoting the inflammatory response and virus dissemination to extra-pulmonary organs during IAV-infection." (PMID 23555246, 2013). "Plasminogen and active plasmin levels were barely detectable in the BAL of uninfected mice but their levels significantly increased during the course of infection." (PMID 23555246, 2013). "The levels of the Rora, SPARC, PLG, G6PC, NR1D2 and AGRP mRNAs were measured by qRT-PCR 24 h, 48 h and 72 h after infection of HepG2 cells with either Ad-RORα or control Ad-GFP." (PMID 21818335, 2011). "On the other hand, the same formulation failed to provide protection using the humanized plasminogen mouse model of invasive lethal infection." (PMID 32156809, 2020). "In the presence of human plasminogen all mice infected with the SIC-expressing AP1 strain were dead by 50 h post-infection, whereas mice infected with the same bacteria in the absence of plasminogen were still healthy at 7 days post-infection." (PMID 30002122, 2018). "This study is the first to show that ANXA2 plays a role in promoting the replication of H5N1 AIV strains through a unique mechanism that does not require the conversion of PLG into plasmin to initiate infection." (PMID 28893180, 2017). "The authors estimated that the inactivation rate of the naturally occurring, glycosylated TFPI by Pla is significantly higher than plasminogen activation by Pla and hence proposed that TFPI inactivation and fibrin formation protect Y. pestis during early stages of the infection." (PMID 23898467, 2013). "The cell viability was assessed after infection of GBS preincubated with or without plasminogen plus tPA." (PMID 23658816, 2013). "We found C. albicans could activate plasminogen to facilitate it to damage host endothelial cells, as determined by assaying LDH release after a 12-h co-culture of HUVECs with C. albicans (multiplicity of infection (MOI) = 0.1) in the presence of plasminogen." (PMID 33115324, 2020). "Although previous study reported C. albicans could bind human plasminogen, no direct evidence for a role in establishing invasive infection was found." (PMID 33115324, 2020). "However, the molecular mechanism of fungal cell walls interacting with host plasminogen and the role of this interaction in establishment of invasive infections have not been elucidated." (PMID 33115324, 2020).